PRIM2 (DNA primase subunit 2)
Description:
Regulatory subunit of the DNA primase complex and component of the DNA polymerase alpha complex (also known as the alpha DNA polymerase-primase complex) which play an essential role in the initiation of DNA synthesis. During the S phase of the cell cycle, the DNA polymerase alpha complex (composed of a catalytic subunit POLA1, an accessory subunit POLA2 and two primase subunits, the catalytic subunit PRIM1 and the regulatory subunit PRIM2) is recruited to DNA at the replicative forks via direct interactions with MCM10 and WDHD1 (By similarity). The primase subunit of the polymerase alpha complex initiates DNA synthesis by oligomerising short RNA primers on both leading and lagging strands. These primers are initially extended by the polymerase alpha catalytic subunit and subsequently transferred to polymerase delta and polymerase epsilon for processive synthesis on the lagging and leading strand, respectively (By similarity). In the primase complex, both subunits are necessary for the initial di-nucleotide formation, but the extension of the primer depends only on the catalytic subunit. Binds RNA:DNA duplex and coordinates the catalytic activities of PRIM1 and POLA2 during primase-to-polymerase switch.
Synonyms: p58; PRIM2A
Tractability: Small molecule: an approved drug acts on it; a structure with a bound ligand is known. PROTAC: ubiquitination databases record sites on it; its protein half-life has been measured.
Gene: Protein-coding gene on chromosome 6 (57,314,805 to 57,646,855, forward strand). Ensembl gene ENSG00000146143.
Subcellular location (Human Protein Atlas): Nucleoplasm
Pathways (Reactome):
DNA Replication: Activation of the pre-replicative complex; DNA replication initiation; Polymerase switching; Processive synthesis on the lagging strand; Removal of the Flap Intermediate
Cell Cycle: Inhibition of replication initiation of damaged DNA by RB1/E2F1; Polymerase switching on the C-strand of the telomere; Telomere C-strand synthesis initiation
Disease: Defective pyroptosis
Gene Ontology:
Molecular function: 4 iron, 4 sulfur cluster binding; DNA-directed RNA polymerase activity; DNA/RNA hybrid binding; protein binding
Biological process: DNA replication initiation; DNA replication, synthesis of primer
Cellular component: alpha DNA polymerase:primase complex; nucleoplasm
Genetic constraint (gnomAD): Loss-of-function variants: 16 observed, 26.27 expected, observed/expected ratio (o/e) 0.61, 90% interval 0.41 to 0.93. The upper end of that interval is the gene's LOEUF score, 0.93, which puts it in group 3 of 6, group 1 being the genes least tolerant of losing a copy. Missense variants: 215 observed, 273.13 expected, observed/expected ratio (o/e) 0.79, 90% interval 0.7 to 0.88. Synonymous variants: 72 observed, 87.7 expected, observed/expected ratio (o/e) 0.82, 90% interval 0.68 to 1.
Homologues: Orthologues: macaque PRIM2 (97% identical), rabbit PRIM2 (91% identical), dog PRIM2 (90% identical), mouse Prim2 (89% identical), pig PRIM2 (89% identical), rat Prim2 (88% identical), guinea pig PRIM2 (76% identical), tropical clawed frog prim2 (68% identical), zebrafish prim2 (65% identical), Caenorhabditis elegans pri-2 (38% identical), Drosophila melanogaster Prim2 (37% identical).
Diseases named in the same sentence as PRIM2 in open-access papers:
PRIM2 is named in the same sentence as 22 diseases in open-access papers, as found by Europe PMC text mining. Sharing a sentence is not in itself a finding about the gene and the disease. The quoted sentences say what the papers report.
lung carcinoma (11 papers, 2021 to 2025). "In this study, we found that high expression of PRIM2 was associated with poor prognosis in lung cancer patients." (PMID 35884433, 2022). "As expected, knockdown of PRIM2 caused severe cellular senescence in lung cancer cells." (PMID 35884433, 2022). "To this end, we wonder whether the expression level of PRIM2 was associated with the prognosis of lung cancer." (PMID 35884433, 2022). "Thus, we wanted to explore the mechanism underlying the high expression PRIM2 in lung cancer from the tumor suppressor angle." (PMID 35884433, 2022). "In lung cancer, DHA inhibits proliferation and colony formation, increases cell death, and induces ferroptosis in lung cancer cells by inactivating the PRIM2/SLC7A11 axis." (PMID 40994946, 2025). "The β-catenin signaling pathway is crucial in lung cancer carcinogenesis, particularly regarding the downregulation of both SLC7A11 and β-catenin expression in cells associated with PRIM2 loss." (PMID 39193342, 2024). "To explore the roles of PRIM2 in lung cancer, we first analyzed the expression of PRIM2 in lung cancer and found that PRIM2 was significantly upregulated in lung adenocarcinoma (LUAD) at the mRNA and protein levels." (PMID 35884433, 2022). "When we knocked down PRIM2 in lung cancer cells, we found that cell growth was inhibited, the cell cycle was arrested, and cellular senescence was promoted." (PMID 35884433, 2022). "Next, we explored the role of PRIM2 in lung cancer and found that knockdown of PRIM2 induced cell cycle arrest, increased DNA damage, and increased cell senescence, leading to decreased lung cancer cell proliferation." (PMID 35884433, 2022). "This is the first time that PRIM2 has been shown to regulate the cell cycle and play a cancer-promoting role in lung cancer, which will lay the foundation for the subsequent exploration of PRIM2." (PMID 35884433, 2022). "In this study, we found that DNA primase subunit 2 (PRIM2) had a high expression level and associated with poor prognosis in lung cancer." (PMID 35884433, 2022).
lung carcinoma (continued). "Last, we must acknowledge that the cancer-promoting role of PRIM2 in lung cancer needs further experimental verification based on strict study." (PMID 35884433, 2022). "Together, these findings demonstrate that PRIM2 expression was elevated in lung cancer and was correlated with poor patient prognosis, suggesting that PRIM2 has the potential to be a biomarker for lung cancer." (PMID 35884433, 2022). "So far, little research has been done on the mechanism of PRIM2 in lung cancer, and it is mainly found that PRIM2 affects the survival of lung cancer patients and participates in ferroptosis." (PMID 35884433, 2022). "The knockdown of PRIM2 enhanced the sensitivity of NCI-H23 cells to dihydroartemisinin therapy, while the overexpression of PRIM2 had the opposite effect, indicating that dihydroartemisinin induced ferroptosis in lung cancer cells by upregulating the PRIM2/SLC7A11 pathway." (PMID 39202965, 2024). "In conclusion, we identified PRIM2 as a potential biomarker and prognostic factor for lung cancer." (PMID 35884433, 2022). "To further explore role of PRIM2, we knocked down PRIM2 in lung cancer H1299 cells and found that knockdown of PRIM2 inhibited the growth of lung cancer cells, which shows PRIM2 promotes lung cancer progression." (PMID 35884433, 2022). "The results showed that the expression of PRIM2 is abnormally increased in lung cancer." (PMID 35884433, 2022). "ROC curve analysis revealed that PRIM2 could statistically distinguish lung cancer patients from normal individuals, producing an area under the curve (AUC) of 0.904 (95% CI: 0.880–0.927; p < 0.0001)." (PMID 35884433, 2022). "To explore the role of PRIM2, we analyzed PRIM2 expression in lung cancer from the TCGA database." (PMID 35884433, 2022). "Additionally, CDK4 expression was significantly reduced in lung cancer cells with PRIM2 knockdown, indicating the cell cycle is suppressed." (PMID 35884433, 2022). "Gene set enrichment analysis (GSEA) found that PRIM2 may promote the progression of lung cancer by mediating cell cycle and DNA damage repair." (PMID 35884433, 2022). "To explore the molecular biological function of PRIM2 upregulation in lung cancer, we firstly divided the lung cancer patients sample from the TCGA database into two groups (high PRIM2 expression group and low PRIM2 expression group) according to the expression of PRIM2." (PMID 35884433, 2022). "In addition, DHA impedes colony formation, proliferation and induction of ferry death in lung cancer cells by blocking the PRIM2/SLC7A11 axis." (PMID 34539408, 2021). "In addition, PRIM2 expression increased with stage and was closely related to the poor prognosis of patients, which indicates that PRIM2 plays an important regulatory role in the occurrence and development of lung cancer." (PMID 35884433, 2022). "In conclusion, we found that PRIM2 has an important regulatory role in the progression of lung cancer, which will provide theoretical support for the clinical diagnosis and treatment of lung cancer, including new biomarkers for the early diagnosis of lung cancer and potential therapeutic targets." (PMID 35884433, 2022).
lung carcinoma (continued). "Dihydroartemisinin (DHA) inhibits lung cancer cell proliferation and colony formation, enhances cell death, and induces ferroptosis by inactivating the polypeptide 2 (PRIM2)/SLC7A11 axis, indicating that the inhibitory expression of PRIM2 may be a potential therapeutic target for lung cancer." (PMID 34630843, 2021). "Dihydroartemisinin downregulate the level of PRIM2/SLC7A11 axis so that induce ferroptosis and inhibits the proliferation of lung cancer cell." (PMID 38738174, 2024). "Although it has been found that PRIM2 antagonizes ferroptosis to play a cancer-promoting role in lung cancer, it has not been demonstrated that this role is dependent on the enzymatic activity of PRIM2." (PMID 35884433, 2022). "Some preclinical studies show that DNA primase subunit 2 (PRIM2) is a negative regulator of DHA-induced ferroptosis in lung cancer cells (NCI-H23) through sustaining SLC7A11 expression, indicating that PRIM2 may plays a DNA primase-independent role in shaping ferroptosis." (PMID 34742351, 2021).
cervical cancer (1 paper, 2021). A primary or metastatic malignant neoplasm involving the cervix. "Pearson correlation analysis showed that the expression of MCM3 and PRIM2 or MCM6 in cervical cancer was obviously positive (R = 0.6387 and R = 0.5443, respectively)." (PMID 34671420, 2021). "The upregulated expression of PRIM2 in cervical cancer enhanced DNA synthesis, accelerated the progression of cell cycle from the G1 to S phase, and promoted the proliferation of cervical cancer cells and the growth of cervical cancer." (PMID 34671420, 2021). "We selected two proteins PRIM2 and MCM6, which have strong correlation with MCM3 and have different expressions in cervical cancer compared with normal cervical tissues." (PMID 34671420, 2021). "PRIM2 and MCM6 were significantly upregulated in cervical cancer tissues by the GEPIA database." (PMID 34671420, 2021). "The results indicate that MCM3, PRIM2, and MCM6 could be used for early detection of cervical cancer and may be used as indicators of prognosis." (PMID 34671420, 2021).
latent infection (1 paper, 2023). "The cell proliferation marker MKI67 as well as genes involved in G1-S and G2-M transition, such as CDK1, CDK2, CCNE2, PRIM2, AKT1, and FOXM1, were significantly downregulated in latent infection compared to actively infected cells." (PMID 38038477, 2023).
ovarian carcinoma (1 paper, 2015). A malignant neoplasm originating from the surface ovarian epithelium. "Our results showed that the PRIM2 gene was more frequently deleted in early stage than in late stage HGS ovarian cancer." (PMID 25916844, 2015). "Therefore, both PRIM2 loss and RAD51 downregulation in HGS cancer may result in utilization of the error-prone repair pathway (e.g. non-homologous end joining) and may contribute to the extensive rearrangements found in HGS ovarian cancer." (PMID 25916844, 2015).
pancreatic cancer (1 paper, 2024). "Similarly, in pancreatic cancer coculture, most of the genetic material was non-annotated followed by AIG1, MCF2L2 and PRIM2 among others." (PMID 38783375, 2024).
pancreatic ductal adenocarcinoma (1 paper, 2025). An infiltrating adenocarcinoma that arises from the epithelial cells of the pancreas. "PRIM2 enhances FAM111B expression in pancreatic ductal adenocarcinoma, which in turn promotes tumor cell proliferation and migration." (PMID 40390043, 2025). "In pancreatic ductal adenocarcinoma, PRIM2 upregulates FAM111B expression, thereby enhancing RNA levels and protein stability." (PMID 40390043, 2025).
prostate carcinoma (1 paper, 2021). A carcinoma that arises from epithelial cells of the prostate gland. "The PRIM2 gene, which is involved in synthesizing the Okazaki fragments in DNA replication, has been discovered as having the highest mutation rate in prostate cancer." (PMID 34573430, 2021).
renal carcinoma (1 paper, 2017). A carcinoma arising from the epithelium of the renal parenchyma or the renal pelvis. "We identified recurrent mutations within an intron of the PRIM2 gene specifically in renal cancer." (PMID 28056774, 2017).
Sepsis (1 paper, 2025). Sepsis is defined as life-threatening organ dysfunction caused by a dysregulated host response to infection. "The SNP with the highest SHAP contribution was an intronic variant located in the PRIM2 gene involved in DNA replication, which is critical in sepsis for its role in apoptosis, oxidative stress, and metabolic changes." (PMID 41473159, 2025). "PRIM2 has been related to consecutive trauma-induced sepsis based on an expression profiling analysis." (PMID 41473159, 2025). "The determination of key genes, such as PRIM2, SYNPR, and RBSN, through pre-operative blood tests could enhance risk stratification, enable early detection of post-operative sepsis, and guide targeted interventions to improve patient outcomes." (PMID 41473159, 2025).
Stroke (1 paper, 2022). Sudden impairment of blood flow to a part of the brain due to occlusion or rupture of an artery to the brain. "In the UKB, we attempted to replicate only the PRIM2 rs199585353 and DOK7 rs149905649 associations observed in the European ancestry group as the number of African ancestry individuals in UKB with stroke was small (n = 101)." (PMID 36672803, 2022).
tumor (11 papers, 2018 to 2025). "LIFR (leukemia inhibitory factor receptor) and PRIM2 are known to promote tumor growth, metastasis, and angiogenesis and increase angiogenic activity and coronary artery disease." (PMID 39048584, 2024). "To validate the clinical relevance of our findings based on public databases, we examined the expression of PRIM2 in tumor tissue, which was collected from the Characteristic Medical Center of The Chinese People’s Armed Police Force." (PMID 35884433, 2022). "The ASE genes that was mostly recurrently observed in both tumor and normal samples had a high allele imbalance, such as AP3P1, BCLAF1, STED8, PRIM2, IL32, SEC22, and MAP2K3." (PMID 30538721, 2018). "We found that PRIM2 was significantly elevated in tumor tissue relative to normal tissues by IHC." (PMID 35884433, 2022). "In our analysis, PRIM2 and MAP2K3 had monoallelic expression patterns in the majority of the cancer cell lines from 9 tumor categories." (PMID 40414875, 2025). "Results showed that the expression of five parent gene (PRIM2, ABCC4, UTRN, ABHD2, and MTHFD2L) was also significant increase in tumor compared to those in normal tissues." (PMID 34852706, 2021).
cancer (9 papers, 2012 to 2025). A tumor composed of atypical neoplastic, often pleomorphic cells that invade other tissues. "In SHH, we identified DMPs in four genes (CDK6, COL25A1, MMP16, PRIM2) that encode proteins which are the target of therapies in clinical trials for other cancers." (PMID 37035203, 2023).
PRIM2 also shares sentences with these, for which no sentence is quoted: coronary artery disease (2 papers); colon cancer (1); gastric cancer (1); glioma (1); lung adenocarcinoma (1); non-small cell lung carcinoma (1); osteosarcoma (1); pituitary tumor (1); prostate tumors (1); rheumatoid arthritis (1).